C4orf33 (chromosome 4 open reading frame 33)
Synonyms: FLJ33703
Tractability: PROTAC: ubiquitination databases record sites on it.
Gene: Protein-coding gene on chromosome 4 (129,093,317 to 129,116,640, forward strand). Ensembl gene ENSG00000151470.
Subcellular location (Human Protein Atlas): Golgi apparatus; Nuclear bodies
Gene Ontology:
Molecular function: protein binding
Genetic constraint (gnomAD): Loss-of-function variants: 13 observed, 17.01 expected, observed/expected ratio (o/e) 0.76, 90% interval 0.5 to 1.22. The upper end of that interval is the gene's LOEUF score, 1.22, which puts it in group 5 of 6, group 1 being the genes least tolerant of losing a copy. Missense variants: 143 observed, 168.22 expected, observed/expected ratio (o/e) 0.85, 90% interval 0.74 to 0.98. Synonymous variants: 47 observed, 56.65 expected, observed/expected ratio (o/e) 0.83, 90% interval 0.66 to 1.06.
Homologues: Orthologues: chimpanzee C4H4orf33 (98% identical), macaque C5H4orf33 (96% identical), pig C4orf33 (90% identical), dog C4orf33 (86% identical), rabbit C4orf33 (85% identical), guinea pig C4orf33 (84% identical), rat C2h4orf33 (83% identical), mouse D3Ertd751e (79% identical), tropical clawed frog c1h4orf33 (61% identical), zebrafish C1H4orf33 (60% identical), Caenorhabditis elegans C33A12.3 (41% identical).
Diseases named in the same sentence as C4orf33 in open-access papers:
C4orf33 is named in the same sentence as 1 disease in open-access papers, as found by Europe PMC text mining. Sharing a sentence is not in itself a finding about the gene and the disease.
C4orf33 shares sentences with these, for which no sentence is quoted: Obesity (1 paper).